TIMP3 (TIMP metallopeptidase inhibitor 3)
Diseases named in the same sentence as TIMP3 in open-access papers (continued):
Sharing a sentence is not in itself a finding about the gene and the disease.
tumor (continued). "Thus, in this heterologous mouse model for Theileria-transformed macrophage dissemination ectopic expression of Flag-Δ169-c-Jun that diminishes MMP9/ADAM19 and increases TIMP3 expression led to ablation of tumour dissemination by the engineered attenuated line." (PMID 25375322, 2014). "In addition, miR-222, by targeting PTEN and tissue inhibitor of metalloproteinases-3 (TIMP3) tumor suppressors, induces tumor necrosis factor (TNF)-related apoptosis-inducing ligand resistance and enhances cellular migration through activation of the Akt pathway and metallopeptidases." (PMID 23028614, 2012). "Moreover, delivery of TIMP-3 to tumor xenografts has confirmed its tumor suppressive activity." (PMID 17032447, 2006). "Finally, the fact that TIMP-3 protein within fibroblasts was found to have no clinicopathological or prognostic value indicates that, at least in our series of tumor samples, TIMP-3 within cancer cells seems to be more strongly correlated with tumor biological behavior than stromal TIMP-3." (PMID 17032447, 2006). "Epigenetic analyses revealed histone modifications (H4K16ac, H4K20me3) and altered methylation of tumor-suppressor genes (PITX2, RASSF1, PTEN, TIMP3)." (PMID 40371330, 2025). "Studies reveal that TIMP3 (24-kDa glycoprotein), a member of the TIMP family of proteins, acts as a potent tumor suppressor by preventing tumor angiogenesis, invasion, and metastasis." (PMID 41009435, 2025). "Promoter methylation analysis was conducted for the following tumor-suppressor genes: ATM (NPAT) with four analyzed CpG sites (CpG 1–4), PITX2 (CpG 1–5), RASSF1 (CpG 1–3), PTEN (CpG 1–6), and TIMP3 (CpG 1–6)." (PMID 40371330, 2025). "Gene effect values approaching –1 suggest that suppression of ITGB1, TIMP3, or BRAF severely compromises tumor cell viability." (PMID 41294900, 2025). "The network of the most promising miRNA-target interactions showed that several tumor suppressor and oncogenic miRNAs target and regulate critical genes, including MYC, CREB1, TIMP3, CCNE1, and TGFB1, which were shown to be involved in WT pathogenesis." (PMID 39473825, 2024). "The protein levels of TIMP3 in the culture supernatants of TOV-21G (CCC histology) and TOV-112D (endometrioid histology) cells, both of which are from grade 3 tumours, were detected using a guided-mode resonance (GMR) bioassay detection system." (PMID 38542164, 2024). "Gene promoter methylation analysis of the following tumor-suppressors was realized: ATM comprising four evaluated CpG sites (CpG 1–4), PITX2 (CpG 1–5), RASSF1 (CpG 1–3), PTEN (CpG 1–6), and TIMP3 (CpG 1–6)." (PMID 38464730, 2024). "With the TIMP-3 expression data provided in TCGA, significantly higher TIMP-3 mRNA expression was observed in UCC with high tumor stage (P < 0.0001), high tumor T status (P < 0.0001) and high lymph node status (P = 0.0005)." (PMID 36860920, 2023). "Our study demonstrated that the non-smoker with TIMP-3 SNP rs9619311 TC + CC genotype may be under higher risk of muscle invasive tumor development, thus these patients may be suitable to receive aggressive therapy at the early stage while further experiments are needed to support this concept." (PMID 36860920, 2023). "Malignant epithelial cells from the prostatectomy tumor site (C4) showed higher expression of MMP-2, -9, and -11, and TIMP-3 than ECs from the benign biopsy site with future cancer development (C2)." (PMID 37108185, 2023). "Like PTEN and TIMP3, LASS2 belongs to the tumor suppressors or, specifically, metastasis suppressors." (PMID 35408800, 2022).
tumor (continued). "In conclusion, we identified the oncogenic role of circCSNK1G3 in RCC progression and demonstrated the regulatory role of circCSNK1G3 induced miR‐181b expression, which leads to TIMP3‐mediated EMT process, thus resulting in tumour growth and metastasis in RCC." (PMID 33560588, 2022). "Tissue inhibitor of metalloproteinases 3 (TIMP3), a member of the TIMP family, has been noted to inhibit tumor growth, angiogenesis, invasion, and metastasis." (PMID 35487956, 2022). "The results showed circCSNK1G3, as an oncogenic role, suppressed TIMP3 by up‐regulating miR‐181b, thereby promoted the EMT process, and finally contribute to the tumour growth and metastasis in RCC." (PMID 33560588, 2022). "It is defined as one of the “oncomiRs”, the cancer-promoting miRNAs, and has been documented to target several tumour suppressor genes (such as PTEN, RHOB, PDCD4, TIMP3) and play a role in signalling pathways (RAS/MEK/ERK, PTEN/PI3K/AKT, and Wnt/β-catenin)." (PMID 36140324, 2022). "Although some tumor suppressors were identified by the KEGG analysis of our comparative proteomics, e.g., TIMP3 and SMAD4, most proteins of the cancer group in our dataset were oncogenic." (PMID 35999337, 2022). "Meanwhile, low expression levels of tissue inhibitors of metalloproteinases (TIMP-3 and TIMP-4) were found in all three tumor lines." (PMID 34620867, 2021). "Conversely, TIMP3 (P = 0.0156), THBS1 (P = 0.0156), and CAV1 (P = 0.0313) were all decreased in tumour stroma EVs compared to normal stroma EVs." (PMID 34596356, 2021). "In tumor angiogenesis, increased H3K9 acetylation was related to over-expression of TIMP3 inhibiting growth of carcinoma cells, while decreased H3K27me3 resulted in the upregulation of TIMP3 and re-expression of anti-angiogenic genes in dormant cells." (PMID 34552922, 2021). "In the same context, upregulation of TIMP-3 expression in Stage III, Grade 3 and Type 2 tumors deduced from this study, points to the involvement of TIMP-3 in tumor progression and treatment outcome." (PMID 35047406, 2021). "Certain tumor suppressor genes specifically in the thyroid are found as PTEN, TIMP3, SLC5A8, DAPK, RAPβ2, and RAP1GAP." (PMID 33669363, 2021). "Five molecules (DAPK1, TIMP3, GRIN2B, SLC5A8, and CDH1) are tumor suppressor genes consistently downregulated and/or hypermethylated in GC and in H. pylori infected children." (PMID 32117120, 2020). "miR-21 activates the EGFR/AKT signaling pathway via targeting tumor suppressor genes such as PTEN, PDCD4, APAF1, TPM1, TIMP3, RECK, FOXO1 and SPRY240." (PMID 32019988, 2020). "TIMP-3-armed HSV treatment of human neural tumor cells in vitro and in vivo inhibited MMP3 levels, increased viral replication in and cytotoxicity of tumor cells as well as VECs, thereby reducing vascular density." (PMID 33167307, 2020). "KLF4 directly activates the expression of the gene coding for tissue inhibitor of metalloproteinases 3 (TIMP3), which acts as a tumor suppressor." (PMID 33266506, 2020). "The methylation status of five tumor-suppressor gene promoters was assessed: ATM including four evaluated CpG sites (CpG 1–4), PITX2 (CpG 1–5), RASSF1 (CpG 1–3), PTEN (CpG 1–6), and TIMP3 (CpG 1–6)." (PMID 33375383, 2020). "This compound inhibits miR-21-5p, promotes the expression of TIMP-3, prevents the phosphorylation of KDR and its downstream factor MAPK, and inhibits the proliferation and migration abilities of HUVECs, blocking tumor angiogenesis." (PMID 32762747, 2020). "The decreased expression and activity of TIMP3 has been reported to correlate directly with an increased CRC invasion and advanced tumor stage." (PMID 30988064, 2019).
tumor (continued). "The observed strong downregulation of TIMP3 and disturbed MMP2/TIMP3 expression ratio can be explained as crucial activities in the ECM remodeling process, enabling creation of a microenvironment conducive to tumor growth." (PMID 31921636, 2019). "Based on the TIMP3 induction capability of MPT0B390, we next investigated the effect of MPT0B390 on tumor angiogenesis." (PMID 31588243, 2019). "Since TIMP3 plays a major role in regulating tumor metastasis, we elucidate how MPT0B390 transcriptionally induces TIMP3 expression." (PMID 31588243, 2019). "The effect of methylation alterations in thyroid carcinogenesis is demonstrated by downregulation of several tumor suppressors thyroid cancer cells, such as; TSHR, PTEN, RASSF1A, CDKN2A, DAPK1, TIMP3, ECAD, and RAP1GAP." (PMID 31835496, 2019). "The decreased TIMP3 expression has been reported to correlate directly with increased CRC invasion and advanced tumor stage." (PMID 30988064, 2019). "Further, decreased TIMP3 expression has been reported to correlate directly with an increased CRC invasion and advanced tumor stage." (PMID 30988064, 2019). "It targets the tumor suppressors such as PTEN, metalloproteinase inhibitor 3 (TIMP3) and HDAC6 in canonical Wnt signaling." (PMID 29977206, 2018). "Therefore, inhibition of TIMP-3 may promote tumor development." (PMID 29467412, 2018). "The overexpression of miR-21 down-regulated the expression of tumor suppressors such as PDCD4 and TIMP3 and promoted cell proliferation, leading to the development of PC." (PMID 29385987, 2018). "It has been reported that EZH2 can attenuate expression of TIMP-2 and TIMP-3 by inducing gene promoter DNA methylation, thereby increasing MMP activity in tumor cells." (PMID 30341286, 2018). "MiR-21 has been shown to affect cell proliferation, invasion, and the clinical outcome by downregulating the expression of tumor suppressors, such as PDCD4, TIMP3, RECK, and KRIT1." (PMID 28466015, 2017). "In relation to the effects of the high fat diets, little influence was observed in mammary gland, whilst in tumor the EVOO groups showed lower levels of RASSF1A and TIMP3 mRNA." (PMID 26401660, 2015). "Wholemount staining of non-tumor-bearing glands from endpoint MMTV-Neu mice revealed that 13 of 22 Neu Timp3+/+ glands were hyperplastic, while only 5 of 37 Neu Timp3−⁄− glands showed evidence of transformation, further supporting this concept." (PMID 25807548, 2015). "Furthermore, miR-21 might be a regulator of tumor growth and this effect may be dependent on TIMP3." (PMID 25587717, 2015). "The present data show that MPT0G013 inhibits angiogenesis by up-regulating TIMP3 gene expression in endothelial and tumor cells, indicating the potential of MPT0G013 as a therapeutic agent with dual activities against tumor growth and angiogenesis." (PMID 25226613, 2014). "In conclusion, the present study showed aberrant tumor-specific methylation alterations for APC, BIN1, BMP6, BRCA1, CST6, ESR-b, GSTP1, P14, P16, P21, PTEN and TIMP3 in the studied cohort." (PMID 22695536, 2012). "The significant reduction of TIMP3 (an endogenous inhibitor of MMPs) and increase of ADAM15 transcripts, shared by both cell lines, emphasize an imbalance of MMPs functions in tumor cells overexpressing CD157." (PMID 22916288, 2012). "Hierarchical clustering showed significant hypermethylation patterns for serum and tumor tissue compared with normal tissue for seven genes (APC, BIN1, BMP6, BRCA1, CST6, P16 and TIMP3)." (PMID 21283676, 2011). "Two-way hierarchical clustering in serum and tumor tissue showed significant hypermethylation patterns of seven genes (APC, BIN1, BMP6, BRCA1, CST6, P16 and TIMP3) compared with normal tissue." (PMID 21283676, 2011). "The expression of MMP-9 or TIMP-2 by tumour cells, MMP-1, 7, 9, 11, 13, or TIMP-3 by fibroblastic cells, and MMP-7, 9, 11, 13, 14, TIMP-1, or TIMP-2 by mononuclear inflammatory cells, was also significantly associated with a higher rate of distant metastases." (PMID 17342087, 2007).
tumor (continued). "Normal colonic tissue from patients with MSI+ and CIMP+ tumours frequently demonstrated high methylation levels, particularly for the P16(INK4A), MLH1, TIMP3 and DAPK genes." (PMID 16421593, 2006). "Matrix metalloproteases, one tissue inhibitor of metalloproteases (TIMP-3) and members of the IGF family are regularly contrarily expressed between primary tumours and lymph node metastases." (PMID 16189523, 2005). "Promoter hypermethylation in 10 tumour-related genes (APC, E-cadherin, GSTP1, hMLH1, MGMT, p15, p16, SOCS1, TIMP3 and TGF-beta RII) was determined by quantitative methylation-specific PCR (MethyLight)." (PMID 15942635, 2005). "Additionally, MCPIP1 regulates the expression of the tumor suppressors PTEN, RECK and TIMP3 in cell lines and in in vivo models of ccRCC, indicating the importance of MCPIP1 expression in tumor development and progression." (PMID 39815326, 2025). "Our data suggests that miR-30d-driven suppression of TIMP3 may diminish ECM integrity and accelerate tumor dissemination." (PMID 41294900, 2025). "This miRNA may contribute to tumor growth, metastasis, and EMT induction in several cancer types by suppressing TIMP3." (PMID 40149537, 2025). "The database indicated a negative correlation between TIMP3 and tumor purity (r = −0.326, p = 1.69 × 10–11." (PMID 41009435, 2025). "The ability of malignancies to penetrate and spread in vitro and in vivo may be restricted through upregulating TIMP-3 and RECK, which could serve to be a target site in anti-tumor treatment." (PMID 41476448, 2025). "The transcriptomic analysis of the Groft scientific group showed a positive correlation between TIMP1 expression and a negative correlation of TIMP4 expression with tumor grade and malignant behavior, while the expression of TIMP3 and TIMP2 remained unchanged." (PMID 38474106, 2024). "TIMP3 and MGP can inhibit tumor growth, invasion, metastasis and angiogenesis." (PMID 37202394, 2023). "Additionally, TIMP3, SPARC, IGFBP3, and IGFBP7 were highly expressed in the Mac_5 cluster, and these genes were involved in immunosuppression, tumor cell proliferation, and angiogenesis." (PMID 37533434, 2023). "Importantly, TIMP3 binds to MMP2 and MMP9, and we have previously reported that GBM MMP2 is expressed by tumor cells whereas MMP9 is expressed by tumor-infiltrative neutrophils." (PMID 37511403, 2023). "In parallel, the scRNA data from 15 PDAC tissues samples also showed higher infiltration of cells expressing SMC/fibroblast markers (PDPN, COL5A1, COL22A1, TIMP3, SPARC, WT1, GFPT2) in samples with higher proportions/fractions of MUC16-expressing tumor (epithelial) cells (n = 7)." (PMID 36816942, 2023). "On the other hand, it was also remarkable that we found high expressions of several factors by ECs from non-tumor areas from prostatectomies (MMP-9 and 11, and TIMP-3) compared with these same cell types from previous benign biopsies in the zone where the tumor arose." (PMID 37108185, 2023). "Intriguingly, TIMP3 KO mice expressing the PyMT or Neu oncogenes under the control of the MMTV promoter exhibited delayed tumor onset or a complete lack of tumor development, respectively." (PMID 36768435, 2023). "Expressed TIMP3, reduced MMP activity, inhibited vasculogenesis, delayed tumor growth." (PMID 36467495, 2022). "TIMP-3 is secreted by most cell types and is sequestered at the cell surface, where it is bound by components of the ECM, while its main function is consisting in tumor suppression." (PMID 36713871, 2022). "Also, miR-181b-5p was upregulated by circular RNA circCSNK1G3 to promote tumor growth and metastasis in RCC via the TIMP3-mediated epithelial-to-mesenchymal transition (EMT) process." (PMID 35938021, 2022).
tumor (continued). "The miR-21 targets include the genespromoting apoptosis (PDCD4 and LRRFIP1), as well as the tumor suppressor genes inhibitinginvasion (RECK and TIMP3) and proliferation(IGFBP3).Furthermore, miR-21 can affect microglial behavior, thus ensuring favorableconditions for tumor growth." (PMID 34707896, 2021). "TIMP3+M3 and S100A8+N3 were both identified as protumoral cell types and related with lymph node metastasis, suggesting that those cells might promote the tumor progression in synergy." (PMID 34659209, 2021). "When signatures from plasma- and ascites-derived sEVs were compared we found significant differences in expression of COL5A1, AEBP1, TIMP3, and ACTB at week 3 of tumor progression, suggesting that ascites-derived sEVs are likely a stronger indicator of tumor presence compared to plasma-derived sEVs." (PMID 34868914, 2021). "We also previously showed that the loss of TIMP3 in cells and in tumors generated in NOD-SCID mice lacking RNase activity led to increased IL-6 expression and was correlated with tumor progression." (PMID 34657130, 2021). "Among these miRNAs, miR-21 has been extensively investigated in different cancers where it was shown to target important tumor suppressors such as, for example, PTEN, SPRY2, TIMP3, PDCD4, RECK, and STAT3, and thus to behave as one of the most important oncogenic miRNAs (oncomiR) identified to date." (PMID 34638467, 2021). "Indeed, both iRP-D26 and iRP-D28A showed upregulation of several genes known to facilitate human EVT and/or tumor cell invasion, including SDC2, TIMP3, MMP14, and ADAM12." (PMID 34154587, 2021). "In this study, we reported high-level expression of FKBP51 in both primary ccRCC tumor samples and cell lines and discovered that the invasion and migration ability of ccRCC cells were promoted by the FKBP51-mediated autophagic degradation of TIMP3." (PMID 34599146, 2021). "TIMP3 gene expression decreased in tumor tissue in CRC patients compared to healthy control, but its levels are increased in tumors compared to adjacent non-tumor tissues." (PMID 32171282, 2020). "During hepatocellular carcinogenesis in vitro and in vivo, miR-221/222 induced TRAIL resistance by regulating tumor suppressors such as PTEN and tissue inhibitor of metalloproteinase 3 (TIMP3), and enhanced cell migration by activating the AKT pathway and metallopeptidase activity." (PMID 33171811, 2020). "Regarding TIMP-3, there are data in agreement with our own findings indicating that TIMP-3 is a naturally occurring inhibitor of angiogenesis that limits vessel density in the vascular bed of tumors and curtails tumor growth." (PMID 31086100, 2019). "For example, in the case of TIMP-3, the C-terminal domain is responsible for its unique ability to bind to the ECM and in the case of TIMP2, the C-terminal domain plays a role in its high affinity binding to the tumor cell surface." (PMID 29393911, 2018). "The immunohistochemical analysis of the tumor tissues also showed a negative correlation between IL-6 and TIMP3 expression." (PMID 29731768, 2018). "KHSRP mainly enhances tumor cell migration and invasion by promoting the maturation of miR-130b, miR-21 and miR-301a and by indirectly inhibiting the expression of their targets, such as endogenous EMT inhibitors BMP6, PDCD4 and TIMP3." (PMID 29254151, 2017). "This conclusion is oversimplified, as both Timp3 and Mtss1 do not always act as tumor suppressors in HCC." (PMID 29050362, 2017). "When combined with Timp3 deficiency, PyMT Timp3−⁄−Tnfr1−⁄− mice have a distinct phenotype such that they failed to delay tumor initiation unlike all other Timp3−⁄−, Tnf−⁄−, or Tnfr1−⁄− cohorts." (PMID 25807548, 2015).